MMP14 (matrix metallopeptidase 14)
Diseases named in the same sentence as MMP14 in open-access papers (continued):
Sharing a sentence is not in itself a finding about the gene and the disease.
metastatic cancers (7 papers, 2016 to 2022). A carcinoma which has spread from the original site of growth to another anatomic site. "MMP-14 is highly expressed in metastatic cancers, is associated with poor prognosis, and a proven clinical target." (PMID 28938563, 2017). "Matrix metalloproteinase-14 (MMP-14) is a clinically relevant target in metastatic cancers due to its role in tumor progression and metastasis." (PMID 28938563, 2017). "Based our results obtained with Fab 3369, we expect that second generation antibodies will achieve a more complete blockade of MMP-14 in a number of metastatic cancer models." (PMID 28938563, 2017). "MMP14 is a clinically relevant target to image and treat several metastatic cancers." (PMID 35565326, 2022). "Given the involvement of MMP-14 in HER2+ cancer cell invasion, it will be interesting to test for the effects of Myc B on Dynactin and MMP-14 activity in these models in future studies aimed at understanding comprehensive effects of actin disruption in metastatic cancers." (PMID 30467396, 2018).
metastatic melanoma (7 papers, 2008 to 2025). A melanoma that has spread from its primary site to another anatomic site. "Therefore, the herein identified MMP14 dependent Notch3 upregulation may prove important in metastatic melanoma progression." (PMID 29712618, 2018). "The genes involved in demethylation partially overlap among clinical subgroups: five genes (EMR3, SEPT9, IL8, MMP14 and SLC22A18) were found to be commonly demethylated in large (Breslow thickness >4 mm), nodular subtype, ulcerated and metastatic melanomas." (PMID 24832207, 2014). "In contrast, the metastatic melanomas express higher levels of genes such as MAGE, GPR19, BCL2A1, MMP14, SOX5, BUB1, RGS20, and more." (PMID 18442402, 2008). "Importantly, MMP14 belongs to a set of up-regulated genes specifically expressed in the transition from nevi to non-metastatic and metastatic melanoma." (PMID 34830157, 2021).
oral cancer (7 papers, 2013 to 2025). "Together, these observations highlight the critical role of MMP-14 in oral cancer progression and support further exploration of strategies to modulate its activity for improved patient outcomes." (PMID 40572725, 2025). "Whatmore, one-way Cox regression analysis showed that three BMGs, LAMA3, MMP14, and GPC2, were significant prognostic predictors in oral cancer patients." (PMID 38877482, 2024).
periodontitis (7 papers, 2015 to 2025). An acute or chronic inflammatory process that affects the tissues that surround and support the teeth. "We conclude that UBC, JUN, and MMP14 are likely an optimal candidate group of host-derived biomarkers, in combination with oral pathogenic bacteria-derived proteins, for detecting periodontitis at its early phase by using salivary samples from patients." (PMID 26793622, 2015). "On the basis of our findings, we propose the cumulative use of UBC, JUN, and MMP14, possibly in combination with oral pathogenic bacteria-derived proteins, as putative biomarkers for early detection of periodontitis to be tested either at the RNA or protein level in salivary samples." (PMID 26793622, 2015). "In another study, the expression of PGE2, MMP-14, and TIMP-1 was evaluated in the gingival tissues of individuals with type 2 diabetes and healthy adults with chronic periodontitis, particularly those experiencing alveolar bone resorption." (PMID 40075856, 2025). "There seems to be a significant increase in MMP expression and activity in chronic periodontitis, especially MMP-1, MMP-3, MMP-7, MMP-8, and MMP-9, with minor contributions from MMP-13 and MMP-14." (PMID 32650590, 2020). "MMP-14 can activate MMP-8 and -13 in vitro, as well as MMP-2, and has been correlated in vivo with active MMP-13 in periodontitis sites." (PMID 28218665, 2017). "Collagenase levels of MMP-14, MMP-8, and MMP-13, have been correlated in chronic periodontitis patients, which suggests either a co-operative role and/or the potential settlement of collagenase activation cascades." (PMID 28218665, 2017). "However, in patients with chronic periodontitis associated with type 2 diabetes, the levels of both MMP-3 and MMP-14 were significantly higher than in healthy or non-diabetic inflamed gingival tissues." (PMID 40075856, 2025). "Other ways to arrest periodontitis could be achieved by MMP activity neutralization using recombinant TIMPs or antibodies directed against MMPs; it was shown that antibodies against MMP-9 and MMP-14 in combination significantly inhibited bone resorption." (PMID 38474009, 2024).
dyslipidemia (6 papers, 2016 to 2025). "We further consider that the expanded metabolic insult rendered by WD feeding, versus the NASH-inducing diet, HFFC (e.g. induction of hepatic steatosis, dyslipidemia, and insulin intolerance), supports an expanded, hepatocyte-extrinsic view of MMP14 metabolic regulation." (PMID 39282008, 2024). "Whether or not loss of MMP14 is involved in human metabolic syndrome, at least partially due to the mechanisms we have uncovered in this report are open questions." (PMID 27478693, 2016).
head and neck squamous cell carcinoma (6 papers, 2006 to 2022). A squamous cell carcinoma that arises from any of the following anatomic sites: lip and oral cavity, nasal cavity, paranasal sinuses, pharynx, larynx, and salivary glands. "Tumors with reduced MMP14 expression compared to normal tissue included head and neck squamous cell carcinoma (HNSC), kidney chromophobe (KICH), prostate adenocarcinoma (PRAD), and uterine corpus endometrial carcinoma (UCEC)." (PMID 34604053, 2021).
malignant glioma (6 papers, 1999 to 2022). A grade III or grade IV glioma arising from the central nervous system. "To examine whether our selective clones could selectively inhibit the activity of MMP14 in a cancer cell model, we performed a gelatin zymography assay with U87-malignant glioma (U87MG) cells, which naturally express high levels of MMP14, MMP9 and MMP2." (PMID 30174795, 2018).
metastatic disease (6 papers, 2006 to 2025). "They found that MMP-14 gene expression, determined using RT-PCR, strongly associated with metastatic disease." (PMID 30532247, 2018). "In such analyses, the proteolytic enzyme, membrane-type matrix metalloproteinase 1 (MT1-MMP, MMP14), is often linked to the metastatic disease with the protease upregulated in tumor cells as well as surrounding stromal cells." (PMID 22164270, 2011). "Furthermore, a high serum MMP-14 level associated with metastatic disease." (PMID 30532247, 2018). "Similarly, in our study, high MMP-14 serum levels associated with metastatic disease." (PMID 30532247, 2018). "Notably, MMP14 remained consistently expressed in both primary and metastatic tumors, while MMP7 and MMP11 were predominantly expressed in the earlier stages." (PMID 40604111, 2025). "However, Hes1 and MMP14 expression levels were unrelated to survival for patients with metastatic diseases." (PMID 26650241, 2015).
nasopharyngeal carcinoma (6 papers, 2018 to 2025). A carcinoma arising from the nasopharyngeal epithelium. "MMP14 expression was distinctly upregulated in nasopharyngeal carcinoma, and its knockdown suppressed the cell migration and invasion through epithelial-mesenchymal transition." (PMID 34868395, 2021). "MMP14 not only promotes cell migration, invasion, and angiogenesis in nasopharyngeal carcinoma and pituitary adenomas but also promotes the secretion of pro-MMP2 and pro-MMP9." (PMID 30886783, 2019).
prostate tumors (6 papers, 2011 to 2024). "Thus, the changes in JIP3 and JIP4 localisation we observed in prostate tumours may cause alterations to cell surface delivery and recycling pathways, which can in turn affect cargo delivery, such as the metalloproteinase MMP14 that are used to degrade extracellular matrix." (PMID 39217195, 2024).
Sepsis (6 papers, 2015 to 2023). Sepsis is defined as life-threatening organ dysfunction caused by a dysregulated host response to infection. "Our study specifically highlights the differential expression of matrix metalloproteinases (MMPs), such as Mmp2-3, Mmp8-9, Mmp14, Mmp17, Mmp19, and Mmp28-29, with significantly higher expression in LPS-induced sepsis compared to CLP-induced sepsis." (PMID 37510271, 2023). "First, the effect of TNFa, which is a pivotal inflammatory mediator of sepsis, acts to induce MMP14 to cleave TIE2." (PMID 38406775, 2023). "In summary, this demonstrates that Tie2 is cleaved by MMP14 possibly at three different sites and targeting these sites might represent a promising therapeutic intervention to treat vascular leakage in sepsis." (PMID 32838837, 2020). "Moreover, this study is the first to suggest that pharmacological MMP14 inhibition in sepsis exerts barrier protective effects predominantly through the inhibition of the injurious Tie2 cleavage at these ectodomain sites." (PMID 32838837, 2020). "Based on the newly identified Tie2 cleavage sites, a possible future approach for the treatment of capillary leakage in sepsis might be to develop an antibody or small molecule that specifically binds with high affinity to the Tie2 cleavage sites hence preventing MMP14 mediated cleavage." (PMID 32838837, 2020). "Moreover, compstatin counteracted the effects of E. coli sepsis on the expression of matrix metalloproteinases MMP8, MMP9 and MMP14." (PMID 26337158, 2015). "Here, we test the therapeutic potential of selectively inhibiting MMP14 using an affinity matured exosite inhibitor termed E2C6 with the primary aim of preventing endothelial Tie2 shedding in vitro in endothelial cells (ECs) and in vivo in murine sepsis and endotoxemia models." (PMID 32838837, 2020).
thyroid cancer (6 papers, 2013 to 2025). "By contrast, other MMPs, including MMP-14, remain largely unexplored in the context of thyroid cancer." (PMID 40869275, 2025). "The expression of MMP14 was found significantly increased in thyroid tumor cell lines and PTC samples and was associated with the invasiveness of thyroid cancer." (PMID 33564303, 2021). "This, together with our data on the inversely correlated expression of PROX1 and MMP14 in the thyroid cancer biopsies, suggests that the increased invasiveness could be due to an increase in MMP14 expression." (PMID 29934628, 2018). "Therefore, to investigate if reciprocal levels of PROX1 and MMP14 would be observed also in thyroid cancer, we performed double-staining IHC for PROX1 and MMP14 on a tissue microarray (TMA) including 57 specimens of which 44 originated from different thyroid cancers and 13 from benign hyperplasias." (PMID 29934628, 2018).
colitis (5 papers, 2020 to 2024). Inflammation of the colon. "The expression of the membrane protease MMP family member MT1‐MMP, also known as MMP‐14, is upregulated in angiogenesis and in inflammatory diseases; however, its potential implications in either IA or colitis were unknown." (PMID 31858727, 2020). "Furthermore, the membrane bound extracellular protease MMP14 has been implicated in the pathogenesis of IBD and thus with tenascin-C’s known link to its expression shows another potential mechanism by which tenascin-C deficiency may be protective in colitis." (PMID 35669358, 2022). "To investigate the possible role of MT1‐MMP (gene name MMP14) in inflammation‐driven IA, we used the DSS‐induced colitis model, a widely recognized model of IA." (PMID 31793743, 2020). "MMP14 inhibition was specific to antitumoral response and did not exaggerate colitis symptoms, as was the case with OPN inhibition." (PMID 38329810, 2024).
colorectal tumor (5 papers, 2014 to 2023). "CIBERSORTx analysis of the LM22 signature matrix suggested that MMP14 expression was associated with the accumulation of TAMs including M2-TAMs in colorectal tumors, with the top three immune cell subsets identified by this analysis being M0-, M2-, and M1-TAMs, respectively." (PMID 36052235, 2022). "We next performed gene expression profiling of MMP14-expressing colorectal tumors with the use of GSEA and CIBERSORTx analysis." (PMID 36052235, 2022). "Our digital pathology platform thus allowed a single cell–based quantitative spatial profiling of MMP14 expression in various cell lineages in the stage III colorectal tumors." (PMID 36052235, 2022). "Colorectal tumor progression was associated with overexpression of MMP-7 and MMP-14, which is also known as a membrane type 1-matrix metalloproteinase (MT1-MMP)." (PMID 28272349, 2017). "Furthermore, a preclinical study of genetically engineered or syngeneic mouse models revealed that the expression of MMP14 in colorectal tumors gave rise to 5-FU resistance through activation of CAFs." (PMID 36052235, 2022). "Further investigations of the role of MMP14+ CAFs in the TME should thus include simultaneous transcriptomic and genomic profiling of colorectal tumors." (PMID 36052235, 2022).
emphysema (5 papers, 2015 to 2024). "Increased MMP-14 levels were also detected in emphysematous lungs of humans, which collectively corroborates a role of MoAM/mono-like macrophages in the development of pulmonary emphysema at the molecular level for both mice and human." (PMID 38348034, 2024). "In addition, exposure to tobacco smoke extract (TSE) exposure can cause human macrophages to release EVs (including exosomes and ectosomes), which contribute to the release of matrix metalloproteinase 14 (MMP14) and may contribute to emphysema." (PMID 33546691, 2021).
endometrial cancer (5 papers, 2007 to 2025). Primary or metastatic malignant neoplasm involving the endometrium (mucous membrane that lines the endometrial cavity). "Given that this cell line express constitutive levels of MMP-2 and MMP-14, and that EN-1078D cells were highly invasive in vitro, this cell line represent an important tool for the characterization and the study of the molecular and cellular mechanisms regulating endometrial carcinoma cell invasion." (PMID 17894888, 2007). "The level expression of MMP-2, MMP-14 and TIMP-2 in EN-1078D cell line is consistent with an endometrial cancer with high invasive potential." (PMID 17894888, 2007).
esophageal squamous cell carcinoma (5 papers, 2016 to 2024). Esophageal squamous cell carcinoma (ESCC) is a type of esophageal carcinoma (EC) that can affect any part of the esophagus, but is usually located in the upper or middle third. "In esophageal squamous cell carcinoma (ESCC), overexpression of miR-133a decreased invadopodia formation-related protein FSCN1 and MMP14 levels." (PMID 34290983, 2021).
non-small cell lung carcinoma (5 papers, 2014 to 2022). A group of at least three distinct histological types of lung cancer, including non-small cell squamous cell carcinoma, adenocarcinoma, and large cell carcinoma. "In the present study, the correlation between the expression levels of semaphorin-3A and MMP-14, and their subsequent prognostic significance in non-small cell lung cancer (NSCLC), was investigated." (PMID 24765144, 2014). "Additionally, TIMP2 influences MMP14 activity, and overexpression of MMP14 is observed in epithelial and stromal cells in non-small-cell lung cancer patients and neurodegeneration and age-related changes." (PMID 36624735, 2022). "In highly invasive and metastatic non-small cell lung cancer (NSCLC), SEMA3A is reduced while the level of MMP-14 is elevated." (PMID 26755661, 2016). "For example, matrix metalloprotease (MMP) genes such as MMP9, MMP14, and MMP15, which are usually overexpressed in non-small cell lung cancer, also have multiple E2F-binding sites in their promoters, and their expression is regulated by the Rb-E2F pathway." (PMID 26555075, 2015).
preeclampsia (5 papers, 2012 to 2023). Preeclampsia is a hypertensive disorder of pregnancy that is characterized by new-onset hypertension with proteinuria presenting after 20 weeks of gestation, and depending on mild or severe forms may initially present with severe headache, visual disturbances, and hyperreflexia. "In a setting with increased concentration of membrane-bound ENG receptors, mass action predicts that more will be cleaved by MMP-14, resulting in increased sENG, which is found in women with preeclampsia and has been suggested to cause endothelial dysfunction." (PMID 23548068, 2013). "MMP-14 has been proposed as a potential therapeutic target to reduce circulating soluble endoglin (sEng) and mitigate clinical manifestations of preeclampsia." (PMID 28726716, 2017). "Our data strongly suggests membrane bound MMP-14 was responsible for producing soluble endoglin in preeclampsia." (PMID 22768148, 2012). "This find identifies a specific drug target for severe preeclampsia; interfering with MMP-14 mediated cleavage of endoglin could decrease soluble endoglin production, ameliorating clinical disease." (PMID 22768148, 2012). "Soluble endoglin (sENG), which is released into circulation after cleavage of trans-membrane ENG by matrix metalloproteinase-14 (MMP-14), is also elevated in preeclampsia." (PMID 23548068, 2013).
renal carcinoma (5 papers, 2018 to 2024). A carcinoma arising from the epithelium of the renal parenchyma or the renal pelvis. "Even though the content of both investigated membrane-type metalloproteinases in renal cancer was similar, the activity of MMP-14 was much higher in both tumor phases compared to that of MMP-15." (PMID 39125675, 2024). "Renal carcinoma cells express Membrane Type 1-Matrix Metalloproteinase (MT1-MMP, MMP-14) to degrade extracellular matrix components and a range of bioactive molecules to allow metastasis and cell proliferation." (PMID 30641935, 2019). "However, our findings suggest that transmembrane metalloproteinase 14 (MMP-14) plays a much more significant and essential role than MMP-15 in the studied renal carcinoma tissues." (PMID 39125675, 2024).
endometriosis (4 papers, 2016 to 2023). The growth of functional endometrial tissue in anatomic sites outside the uterine body. "Membrane type-1 matrix metalloproteinase (MT1-MMP, MMP14) is often deregulated in different cancer tissues and body fluids of human cancer patients; however, MT1-MMP levels in endometriosis and adenomyosis patients are currently unknown." (PMID 37893104, 2023). "Several studies have reported higher expression of MMP-2, MMP-9, MMP-14, and MMP-24 in the eutopic endometrium or ectopic lesions of women with endometriosis, as compared to levels in women without endometriosis." (PMID 31636643, 2019).
kidney cancer (4 papers, 2015 to 2024). Primary or metastatic malignant neoplasm involving the kidney. "However, MMP-14 demonstrated a much higher activity in both grades of kidney cancer, when compared to MMP-15." (PMID 39125675, 2024). "Despite their similar contents, MMP-14 seems to be the dominant MMP in kidney cancer." (PMID 39125675, 2024). "Moreover, this collaboration can also be applied to the induction of the HRE-containing MT1-MMP (MMP14) gene in kidney cancer cells, in which the function of von Hippel-Lindau (VHL) protein is lost, and therefore, HIFs are expressed even under normoxia." (PMID 26703734, 2015). "For instance, earlier studies demonstrated the overexpression of MMP9, MMP12, MMP14, and MMP16 in breast and kidney cancers, emphasizing their role in tumor progression and metastasis." (PMID 39493455, 2024).